ADAM22 (ADAM metallopeptidase domain 22)
Description:
Probable ligand for integrin in the brain. This is a non catalytic metalloprotease-like protein. Involved in regulation of cell adhesion and spreading and in inhibition of cell proliferation. Neuronal receptor for LGI1.
Synonyms: ADAM 22; MDC2; DEE61; EIEE61
Tractability: Small molecule: it has a high-quality binding pocket. Antibody: UniProt places it where antibodies can reach, with high confidence; its Gene Ontology location is reachable by antibodies, with high confidence; UniProt predicts a signal peptide or a membrane-spanning region. PROTAC: its protein half-life has been measured.
Gene: Protein-coding gene on chromosome 7 (87,934,136 to 88,202,889, forward strand). Ensembl gene ENSG00000008277.
Subcellular location: Cell membrane; Cell projection, axon
Subcellular location (Human Protein Atlas): Cell Junctions
Pathways (Reactome):
Developmental Biology: LGI-ADAM interactions
Gene Ontology:
Molecular function: protein binding; integrin binding; metalloendopeptidase activity; signaling receptor activity; metallopeptidase activity
Biological process: regulation of AMPA receptor activity; central nervous system development; negative regulation of cell adhesion; positive regulation of synaptic transmission; proteolysis; regulation of AMPA glutamate receptor clustering; regulation of synapse assembly
Cellular component: plasma membrane; trans-synaptic protein complex; axon; membrane; postsynaptic density membrane
Genetic constraint (gnomAD): Loss-of-function variants: 41 observed, 102.61 expected, observed/expected ratio (o/e) 0.4, 90% interval 0.31 to 0.52. The upper end of that interval is the gene's LOEUF score, 0.52, which puts it in group 2 of 6, group 1 being the genes least tolerant of losing a copy. Missense variants: 795 observed, 992.57 expected, observed/expected ratio (o/e) 0.8, 90% interval 0.75 to 0.85. Synonymous variants: 331 observed, 347.3 expected, observed/expected ratio (o/e) 0.95, 90% interval 0.87 to 1.04.
Gene-disease validity (ClinGen):
ClinGen rates the evidence that ADAM22 causes each of these diseases.
developmental and epileptic encephalopathy (autosomal recessive): Definitive. An epilepsy associated with developmental impairment that may be due to either the underlying etiology or the superimposed epileptic activity, or both.
Homologues: Orthologues: macaque ADAM22 (96% identical), chimpanzee ADAM22 (93% identical), pig ADAM22 (93% identical), guinea pig ADAM22 (89% identical), rat Adam22 (88% identical), mouse Adam22 (88% identical), dog ADAM22 (85% identical), rabbit ADAM22 (84% identical), tropical clawed frog adam22 (72% identical), zebrafish adam22 (62% identical). Paralogues in human: ADAM11 (43% identical), ADAM23 (40% identical), ADAM19 (26% identical), ADAM9 (24% identical), ADAM12 (24% identical), ADAM33 (23% identical), ADAM15 (23% identical), ADAM21 (21% identical), ADAM8 (21% identical), ADAM30 (21% identical), ADAM20 (21% identical), ADAM28 (20% identical), and 8 more.